ARID1A (AT-rich interaction domain 1A)
Diseases named in the same sentence as ARID1A in open-access papers (continued):
Sharing a sentence is not in itself a finding about the gene and the disease.
cancer (continued). "ARID1A and ARID1B mutations co-occur in patients from multiple cancer types and >30% of ARID1A-mutant cell lines harbor ARID1B-inactivating mutations; thus, even the combined loss of the paralogue pair is tolerated, and potentially beneficial to cancer cells." (PMID 40239999, 2025). "ARID1A mutations have been linked to endocrine resistance in cancers, particularly in the context of hormone-driven cancers." (PMID 40016470, 2025). "Given the high prevalence of ARID1A inactivating mutations across cancer types, this broad and cancer-specific ERN fragility is of high clinical significance." (PMID 40239999, 2025). "ARID1A is the most frequently mutated subunit of the SWI/SNF chromatin remodeling complex in cancer." (PMID 40750787, 2025). "In the context of EC, MuTect2 has been instrumental in uncovering mutations in key genes such as PTEN, PIK3CA, and ARID1A, which are frequently altered in this cancer type." (PMID 39858102, 2025). "Preclinical reports of BRCA-related models indicate that ATR and PARPi co-treatment can overcome homologous recombination restoration and PARPi resistance, making this approach promising for targeting ARID1A-deficient cancers." (PMID 41514650, 2025). "Collectively, these studies underline the importance of PI3K/AKT signaling in cancers with ARID1A deficiency and PIK3CA co-mutations." (PMID 41514650, 2025). "Loss of function and loss of expression of ARID1A is a driving force behind the initiation and progression of cancers." (PMID 40429787, 2025). "By linking ARID1A loss to these processes, the role of chromatin remodeling in genome maintenance and immune modulation is highlighted, offering potential targets for cancer therapy." (PMID 40750787, 2025). "The combination of low GSH levels and GPX4 activity in ARID1A-deficient cancer cells is thought to significantly increase the susceptibility to ferroptosis." (PMID 40369167, 2025). "As one of the most mutated epigenetic regulators in cancer, ARID1A seems to have a context dependent role in different cancers." (PMID 39885328, 2025). "A study of the molecular mechanism underlying ARID1A’s role in cancer development, with prognostic implications and pathological uniqueness, remains unexplored." (PMID 41514650, 2025). "ARID1A deficiency leads to increased cancer stemness through epithelial‐mesenchymal transition (EMT), causing SCC chemotherapy resistance." (PMID 39779467, 2025). "Given the high frequency of ARID1A loss or inactivation in cancer, ARID1A loss has been increasingly exploited in cancer target discovery and precision oncology." (PMID 40369167, 2025). "ARID1A is frequently mutated across various types of cancers, with loss-of-function mutations being the most prevalent." (PMID 40406134, 2025). "ATR inhibitors (ATRi) are in clinical development for treating various cancers, including those with high replication stress, such as is elicited by ARID1A deficiency, but the cellular mechanisms that determine ATRi efficacy in such backgrounds are unclear." (PMID 39779698, 2025). "Loss of ARID2 has been associated with increased tumor growth, impaired DNA repair, and heightened metastatic potential, while ARID1A deficiency promotes cancer cell proliferation and invasion, including bone metastasis." (PMID 40872531, 2025). "In adult cancers, inhibiting EZH2, a component of PRC2, has been successful in restoring immunogenicity in adult cancers with ARID1A mutations 38,39." (PMID 40082458, 2025). "ARID1B exists in the SWI/SNF chromatin remodeling complex in an exclusive manner with ARID1A and has been identified as a major mutated gene in various cancers in recent years." (PMID 39932052, 2025). "Noteworthy, the PDO model that was used in this model also harbored a pathogenic cancer gene census mutation in ARID1A (p.Q473∗), a component of the SWI/SNF chromatin remodeling complex." (PMID 40678543, 2025).
cancer (continued). "It is also worth noting that in some cancers, ARID1A loss has been associated with resistance to certain chemotherapies." (PMID 40429787, 2025). "In cancer, subunits of chromatin remodelers are frequently mutated–for instance, ARID1A, ARID1B, and PBRM1 (components of the SWI/SNF complex) are mutated in various cancers." (PMID 41234540, 2025). "Supporting a central role of these genes in tumorigenesis, mice genetically engineered to express inactivated Smarca4, Arid1a, Smarcb1, or Pbrm1 alleles are prone to cancer." (PMID 41387924, 2025). "The prognostic impact varies with early vs. advanced cancers, displaying better survival rates for patients that experience early-stage ARID1A loss with endometrioid endometrial carcinoma patients." (PMID 40429787, 2025). "Since KEAP1 and ARID1A are commonly mutated in cancer, we compared mRNA expression of KEAP1 and ARID1A in a large cohort of solid tumors of various origins from The Cancer Genome Atlas (TCGA) datasets." (PMID 39272807, 2024). "ARID1A is the most frequently mutated subunit of the chromatin remodelling complex and the most commonly mutated gene in cancers." (PMID 38166741, 2024). "Preclinical data suggest that ARID1A deficiency sensitizes cancer cells to PARP in both in vitro and in vivo models with inhibitors, a process mechanistically linked to DNA damage repair." (PMID 39697230, 2024). "Recently, we revealed the mutational landscape of the human kinome and additional cancer-related genes and found deleterious mutations in ARID1A, a component of the SWI/SNF chromatin-remodeling complex, in 46% of OCCC patients." (PMID 38858765, 2024). "Given the high frequency of ARID1A loss or inactivation in cancer, the exploitation of anticancer therapeutics based on ARID1A status has attracted attention." (PMID 38811536, 2024). "A comprehensive study across multiple cancer types demonstrated better survival rates in EC patients with ARID1A mutations who undergone ICB therapy." (PMID 39902047, 2024). "Among the genes encoding the SWI/SNF complex subunits, ARID1A gene is the most frequently mutated in human cancers, with an overall mutation rate of ~ 6%." (PMID 38229120, 2024). "BLC7A11 expression is impaired in ARID1A-deficient cancer cells, leading to decreased cellular levels of the antioxidant glutathione (GSH)." (PMID 39609317, 2024). "For example, mutations in ARID1A/B (AT-rich interactive domain-containing protein 1A/B) are among the most common aberrancy in human cancers." (PMID 39057032, 2024). "In the search for key genes mediating the aggressive phenotype caused by ARID1A loss, we analyzed 3 Gene Expression Omnibus (GEO) datasets that contain RNA sequencing data from ARID1A-depleted cancer cells." (PMID 38229120, 2024). "ARID1A mutations are associated with high expression of programmed cell death-ligand 1 (PD-L1) and MSI-high, and ICIs are generally effective in treating ARID1A-mutated cancers." (PMID 38893118, 2024). "ARID1A is frequently mutated in cancer and the majority of ARID1A mutations are inactivating mutations that cause a lack of ARID1A protein expression." (PMID 39338919, 2024). "Similar consequences were observed in other cancers where Arid1a loss increased stemness-associated genes." (PMID 39123453, 2024). "Further mechanistic studies and clinical trials are needed to determine the efficacy of cancer targets driven by ARID1A mutations." (PMID 38365747, 2024).
cancer (continued). "Therapeutic strategies leveraging DNA-damaging drugs such as PARP and ATR inhibitors to induce synthetic lethality in ARID1A-mutated cancers have emerged." (PMID 38914477, 2024). "Despite an increasing body of evidence documenting context-specific consequences of ARID1A loss in cancer, there remains a critical gap in knowledge as to how to selectively treat patients harboring these lesions." (PMID 39272807, 2024). "ARID1A mutations have been identified in many cancers, including ovarian clear cell carcinoma, endometrial cancer, gastric cancer, hepatocellular carcinoma, breast cancer, pancreatic cancer, bladder cancer, and renal cancer." (PMID 38835016, 2024). "While SMARCB1 mutations cause malignant rhabdoid tumors and epithelioid sarcoma, the dysfunction of ARID1A predisposes one to a wide variety of cancers, including ovarian clear cell carcinoma, endometrioid carcinoma, neuroblastoma, and bladder cancer." (PMID 38396925, 2024). "In almost all cancer cases, ARID1A mutations result in loss of ARID1A expression, which raises difficulties in making ARID1A therapeutically targetable." (PMID 38587186, 2024). "Arid1a mutations often correlate with the DNA damage repair genes enabling synthetic lethality targeting in Arid1a-mutant cancers." (PMID 39123453, 2024). "The high mutation rate of ARID1A in various cancer types highlights its clinical relevance as a promising biomarker for further therapeutic studies." (PMID 38587186, 2024). "For example, BRG1-mutated cancer cells are dependent on the presence of BRM, whereas ARID1A-mutated cancer cells are vulnerable to the deletion of ARID1B." (PMID 38396925, 2024). "Several recent studies have implicated a role for ARID1A loss in driving cancer progression, including HNSC." (PMID 38358974, 2024). "In recent years, there has been a growing body of evidence indicating the presence of somatic mutations in cancer-associated genes including ARID1A, PIK3CA, KRAS, or PPP2R1A in endometriotic lesions." (PMID 38600147, 2024). "While ARID1A mutations show promise as predictive biomarkers, their role in early cancer detection and other biomarker studies is under investigation." (PMID 38610698, 2024). "ARID1A, a tumor suppressor gene frequently mutated in various cancers, exhibited multiple novel variants." (PMID 39296440, 2024). "Nevertheless, loss of ARID1A is widely recognized as an enabling factor for cancer development and progression." (PMID 39272807, 2024). "The implications of Arid1a mutations in OS have only been superficially studied using cancer cell lines." (PMID 39123453, 2024). "The ARID1A gene, frequently mutated in cancer, encodes the AT-rich interactive domain-containing protein 1A, a key component of the chromatin remodeling SWI/SNF complex." (PMID 39764114, 2024). "This research paves the way for identifying and categorizing which ARID1A mutations are most pathogenic, potentially guiding the development of targeted therapies tailored to specific mutation profiles in cancer treatment." (PMID 39764114, 2024). "Mutations in the genes encoding BAF subunits occur in approximately 20% of all human cancers with Arid1a being the most frequently mutated." (PMID 39123453, 2024). "Genetic dependencies of ARID1A have been used to suggest novel therapeutic avenues against ARID1A-deficient cancer cells." (PMID 39272807, 2024). "Arid1a is a commonly mutated gene in this cancer type, with a reported mutation frequency ranging from 30% to 50%." (PMID 39123453, 2024). "Recent studies have shown that ARID1A has a synthetic lethal interaction with several cancer-associated proteins, including EZH2, HDAC6, GCLC, and AURKA." (PMID 38811536, 2024). "Studying the function of ARID1A is essential for a more precise understanding of the function of ARID1A, as well as matching cancer patients carrying ARID1A mutations with homologous drugs to optimize efficacy." (PMID 39697230, 2024).
cancer (continued). "Given the impact of ARID1A deficiency on the immune response, ARID1A has been proven a promising biomarker for immunotherapy in multiple cancers." (PMID 38555560, 2024). "As a subunit of the SWI/SNF chromatin-remodeling complex, which has been identified as the most commonly mutated chromatin modulator in human cancers, ARID1A is mutated in approximately 10% of patients with CRC." (PMID 38811536, 2024). "Several studies have established an association between dysfunctional DDR pathways in cancers with Arid1a mutations." (PMID 39123453, 2024). "The loss of ARID1A occurs in a variety of human cancers and de-regulates gene expression by disrupting SWI/SNF occupancy at enhancers, leading to the initiation of liver cancer." (PMID 38390898, 2024). "ARID1A, in most cases, acts as a cancer suppressor, while the loss of ARID1A leads to increased cell proliferation." (PMID 39769182, 2024). "This is out of sync with studies on other cancer types that defined mutation in ARID1A as a predictive biomarker for ICI response." (PMID 39902047, 2024). "Despite a growing understanding of the consequences of ARID1A loss in cancer, there remains limited targeted therapeutic options for ARID1A-deficient cancers." (PMID 39272807, 2024). "Despite a high incidence of mutations across cancers, precision medicine options for patients harboring ARID1A mutations in cancer remain limited and unspecific." (PMID 39272807, 2024). "An interesting study found that ARID1A-deficient cancer cells are specifically vulnerable to the inhibition of the glutamate-cysteine ligase synthetase catalytic subunit (GCLC), an important enzyme for GSH synthesis." (PMID 38203758, 2024). "In this study, a drug-sensitivity screen in ARID1A-deficient cancer cells identified unique hits: PRIMA-1 and APR-246; both of which inhibit the activity of the antioxidant metabolite glutathione (GSH) by covalent binding to thiols." (PMID 36980292, 2023). "The MAPK pathway can also be activated by crosstalk with the activated PI3K/Akt pathway in ARID1A-deficient cancers or by upstream KRAS mutations." (PMID 38071325, 2023). "As the only gene mutation which was correlated with unfavorable prognosis, we further investigated how ARID1A mutation correlated with the alteration of the cancer proteome, namely alterations of related proteins and pathways." (PMID 36788224, 2023). "More research is needed to explore the potential benefits of this combination therapy in the context of ARID1A‐deficient cancers, including GC." (PMID 38041544, 2023). "Considering the uncertainties and the current evidence of the literature, we analyzed the data of our population of ARID1A-mutated cancers." (PMID 37711591, 2023). "Genome stability, which essential for cell survival, is compromised in ARID1A-deficient cancer cells." (PMID 36890819, 2023). "ARID1A is mutated in a wide range of cancers, especially in those arising from ectopic or eutopic endometrium, including EAOC." (PMID 37627318, 2023). "Cancer cells with ARID1A mutations tend to be less affected by ARID1A depletion than those without mutations." (PMID 36980292, 2023). "These trials will yield important insights into the potential of these therapies to enhance the outcomes of patients with ARID1A‐mutated cancers." (PMID 38041544, 2023). "Genes encoding subunits of the SWI/SNF chromatin-remodeling family, in particular ARID1A, are among the most frequently found mutated genes in many different types of human cancer." (PMID 37470997, 2023). "Given the prominent role of ARID1A in cancer, iterative insights into how to target ARID1A-deficient cancers by harnessing the immune-metabolic vulnerability are critically needed." (PMID 36980292, 2023). "Its gene ARID1A is frequently mutated and ARID1A levels are lowered in several human cancers, especially gynecologic ones." (PMID 37627124, 2023).
cancer (continued). "We will focus in particular on emerging strategies for the targeted therapy of ARID1A-deficient cancers by exploiting immune-metabolic vulnerability elicited by ARID1A loss to enhance antitumor immune response." (PMID 36980292, 2023). "Recent research has indicated that the loss of ARID1A can promote proliferation, migration and invasion in cancer cells by activating the AKT signalling pathway." (PMID 38041544, 2023). "Exploring the interactions and outcomes of combining immunotherapy with targeted therapy in ARID1A‐deficient cancers is essential for advancing treatment options and potentially enhancing patient outcomes." (PMID 38041544, 2023). "An analysis of TCGA data showed that ARID1A deficiency is associated with higher mutation load across multiple cancer types and is enriched in dMMR/MSI cancers." (PMID 38275587, 2023). "The role of ARID1A loss in the pathogenesis of some of the most common human cancers is discussed, with a particular emphasis on gynaecological cancers." (PMID 38275587, 2023). "In conclusion, these results suggest that targeting ERK holds promise as a therapeutic strategy for treating ARID1A-mutated cancers." (PMID 38071325, 2023). "Mutations in SWI/SNF subunits are found in over 20% of human cancers, with ARID1A being the most frequently mutated subunit." (PMID 37470997, 2023). "Subsequent clinical studies have confirmed that ARID1A-deficiency is enriched in MSI cancers of the endometrium, stomach and colorectum." (PMID 38275587, 2023). "Several targeted agents have shown promise in the context of ARID1A‐deficient cancers, including inhibitors of YES1, cell cycle modulators and ARID1B." (PMID 38041544, 2023). "Many cancer reports have shown that ARID1A deficiency impairs the chromatin remodelling complex function, resulting in dysregulation of the carcinogenic gene expression." (PMID 38017409, 2023). "Here, we summarize the current understanding of the epigenetic and metabolic mechanisms underlying the antitumor immune response in ARID1A-deficient cancers." (PMID 36980292, 2023). "First, loss of ARID1A through genetic or epigenetic inactivation, as occurs frequently in human cancers, contributes to tumorigenesis." (PMID 38071325, 2023). "A recent study discovered that the SWI/SNF complex gene (especially the ARID1A gene) has a high mutation rate in various cancers and is associated with high TMB status and MSI subtypes." (PMID 38008753, 2023). "Though the mutant OCCC was discovered recently, the metastatic mechanism of ARID1A mutant ovarian clear cell cline and therapeutic strategies for ARID1A-mutant cancers remain less reported; thus, associated investigations are needed." (PMID 37238613, 2023). "This led to the development of clinical trials involving BET inhibitors as single agents or in combination with existing treatment options in multiple human cancers bearing ARID1A deficiency." (PMID 36890819, 2023). "These included ARID1B, the paralog of which, ARID1A, is among one of the most frequently mutated genes in cancer, SMARCA4, and SMARCA2." (PMID 37500730, 2023). "In particular, ARID1A loss in cancer cells leads to increased cell proliferation, migration, and invasion, as well as reduced cell apoptosis and chemosensitivity." (PMID 36695883, 2023). "Overall, these findings open up a new avenue to target ARID1A-mutated cancers through selectively modulating cancer cell intrinsic innate immunity to potentiate the antitumor efficacy of immunotherapy." (PMID 36980292, 2023). "Functional genomics studies have revealed that genes encoding subunits of SWI/SNF are collectively mutated in 20–25% of all human malignancies, among which ARID1A is the most frequently mutated subunit in a broad spectrum of human cancers." (PMID 36980292, 2023).